VCAM1 (vascular cell adhesion molecule 1)
Diseases named in the same sentence as VCAM1 in open-access papers (continued):
Sharing a sentence is not in itself a finding about the gene and the disease.
tumor (continued). "The increased VCAM1 expression in ECs may promote the interaction of TCs and ECs, which facilitates tumor metastasis." (PMID 32993785, 2020). "Additionally, we stained for E-selectin, ICAM-1, and VCAM-1 on tumor endothelial cells roughly 24 hours post FUS+MBs BTB/BBB opening in intracranial B16F1cOVA and in the less immunogenic B16F1 tumors." (PMID 32754281, 2020). "Blocking VCAM-1 in vitro and in vivo reduced tumor-mediated lymphatic permeability and lymphatic invasion, suggesting reducing tumor-induced lymphatic vessel permeability may be a feasible approach to regulate lymphatic metastasis." (PMID 32244922, 2020). "To examine whether VCAM-1 promotes PDAC proliferation, we first evaluated the effect of VCAM-1 overexpression or knock-down on tumor growth in vitro." (PMID 33273652, 2020). "The current findings demonstrate that VCAM1 promotes tumor progression in CRC." (PMID 32793471, 2020). "To gain more insight into the mobilization of HPCs, we analyzed the expression of genes that regulate HPC maintenance and attraction in the bone marrow (CXCL12, c-kit ligand, angiopoietin-1, vascular cell adhesion molecule-1 and osteopontin) in tumor-bearing mice." (PMID 33603745, 2020). "The interaction between neutrophils and tumor cells is hypothesized to be mediated by VCAM-1 and results in the formation of CTC–neutrophil clusters endowed with a higher metastasis-forming potential compared to CTCs that do not interact with neutrophils." (PMID 32369910, 2020). "In addition, IR-induced inflammatory cytokines—IL-1β, tumor necrosis factor (TNF)-α, and type I and II IFNs—affect the upregulation of vascular cell adhesion molecule 1 (VCAM-1) on tumor endothelium." (PMID 31261963, 2019). "Endothelial activation correlates with tumor cell survival within the lung vasculature, and E-selectin and VCAM-1 might facilitate tumor cell adherence to the endothelium directly or via bound platelets." (PMID 30907747, 2019). "Furthermore, TECs have been described as being “activated” and “chronically inflamed”; they express adhesion molecules ICAM-1, VCAM-1, and E-selectin, through which they interact with proinflammatory and tumor cells." (PMID 31600937, 2019). "In these cancers, VCAM-1 expression correlated with the tumor grade." (PMID 31340603, 2019). "Additionally, it was demonstrated that VCAM-1 expression increases with tumor progression in a BrM mouse model." (PMID 31396225, 2019). "Moreover, monocytic cells expressing α4-integrin can bind VCAM-1 present on the surface of tumor cells." (PMID 31447834, 2019). "VCAM-1 regulates tumour angiogenesis by enabling endothelial cell adhesion." (PMID 31217905, 2019). "It was also found that CAFs promoted M2 macrophages recruitment in tumor tissue in vivo, and after VCAM-1 knocking-down in tumor cells or depletion of macrophages, the pro-tumor effect of CAFs was partly abolished, but no change was observed in NK cells infiltration." (PMID 30894509, 2019). "Additionally, paracrine TXA2 signaling generates a favorable environment for tumor cell seeding through vascular constriction and induction of E-selectin and VCAM-1 through the TP receptor on endothelial cells." (PMID 30907747, 2019). "However our results support that using VCAM-1 as a tumor inflammatory marker should be carefully considered due to the potential expression of VCAM-1 by tumor cells themselves." (PMID 31340603, 2019). "The ability of VCAM-1 expressed by endothelial cells to bind tumor cells suggest that it could contribute to metastatic spread." (PMID 31340603, 2019). "VCAM-1 is also involved into chemoresistance and tumor immune escape." (PMID 31340603, 2019). "In the last few years, a growing interest into VCAM-1 expression on tumor cells has emerged." (PMID 31340603, 2019). "Our results showed that the TMZ-resistant subline had lower levels of TNF-α-induced VCAM-1 than that of the parental U251 cells, which may benefit the tumor microenvironment by achieving immune evasion." (PMID 29301329, 2018).
tumor (continued). "Several VCAM-1 modulators further show the relationship of VCAM-1 in tumor metastasis." (PMID 29614819, 2018). "Taken together, these results suggest that targeting VCAM-1 may be an effective strategy for regulating tumor metastasis." (PMID 29614819, 2018). "Just as VCAM-1 is instrumental in facilitating leukocyte adhesion to the endothelium under inflammatory conditions, it has been shown to play a pivotal role in the adhesion and invasion of tumour cells." (PMID 29772648, 2018). "Additionally, our recent studies also suggest that the Ig-like domain 6 of VCAM-1 is a potential therapeutic target in transplant rejection, angiogenesis, and tumor cell invasion." (PMID 29614819, 2018). "Vascular cell adhesion molecule-1 (VCAM-1) is bound up with tumor cell adhesion and metastasis." (PMID 30513613, 2018). "The upregulation of VCAM-1 expression on endothelial cells could facilitate the increased adhesion of tumour cells, while its decreased expression in angiogenic vessels might allow tumour cells to escape immunosurveillance via reduced leukocyte infiltration." (PMID 29772648, 2018). "This decreased accumulation of T cells around tumor cells may contribute to the ability of VCAM-1 expressing tumor cells to escape immune attack." (PMID 29301329, 2018). "Although the expression of ICAM-1 and VCAM-1 were significantly increased when endothelial cells were treated with PT, we demonstrated that this effect is not linked to the PT-evoked tumor cell adhesion." (PMID 29100413, 2017). "Moreover, recent studies have indicated that TAMs and tumor-associated neutrophils (TANs) can also contribute to tumor cell egress and survival via NCOA1, CCL18, VCAM1, ICAM1 etc." (PMID 28591712, 2017). "Therefore, we examined the expression of ICAM-1 and VCAM-1, the two well-established CAMs with a key role in tumor metastasis." (PMID 28903329, 2017). "Recently, some groups have also suggested roles for VCAM-1 in tumor progression and metastasis." (PMID 28272300, 2017). "Hence, this study aimed to determine the circulating and tumoural protein expression of TNF-α and the adhesion molecules: L-Selectin and VCAM-1 in primary tumours of PTC patients in relation to their expression in patients with benign thyroid diseases." (PMID 26881177, 2016). "Following 3 weeks of tumor growth, VCAM-1 mRNA levels were at the control levels in mice fed all experimental diets, except the SeGP65 fed group, which exhibited a significant decrease in VCAM-1 mRNA levels compared with both control tumor and the GP65 control." (PMID 26706037, 2016). "TAMs can be identified by increased integrin receptor VCAM1 expression during tumor progression." (PMID 27367025, 2016). "These NCR+ ILC3s interacted with tumor cells and tumor-associated fibroblasts via their NKp44 receptor to trigger production of LTαβ, which resulted in the activation of endothelial cells and mesenchymal stem cells, including upregulation of ICAM-1 and VCAM-1." (PMID 27752256, 2016). "Consistent with VEGF-stimulation of tumor endothelial cells being associated with lower expression of endothelial activation markers, B16.F10 tumors express higher levels of VEGF and lower levels of endothelial ICAM-1 and VCAM-1 than T241 tumors." (PMID 27385210, 2016). "We propose that NF-κB dependent tumor-associated inflammation co-participate in malignant progression concomitant to normal hematopoietic failure through disruption of CXCL12/CXCR4 and VLA4/VCAM-1 communication axes." (PMID 27594840, 2016). "Importantly, although the levels of VCAM-1 correlated with features of tumor burden (such as β2-microblobulin), the prognostic significance of serum VCAM-1 was independent of ISS stage." (PMID 27232930, 2016). "Further, in the present study, VCAM-1 expression was significantly overexpressed in the PTC patients with larger tumour size, presence of lymph node metastasis and unifocal tumours, and presence of extrathyroidal extension of tumours as compared to their respective counterparts." (PMID 26881177, 2016).
tumor (continued). "The expression of L-Selectin and VCAM-1 significantly correlated with aggressive tumor behavior." (PMID 26881177, 2016). "Likewise, NFκB is constitutively activated in primitive AML cells, and it reportedly induces VCAM-1 expression to regulate MSC accumulation at tumor sites." (PMID 26956049, 2016). "The adhesion molecules evaluated in this study, namely ICAM-1, VCAM-1 and ALCAM, are known to be involved in tumor cell attachment to the vascular endothelium and are directly implicated in the progression of tumor growth, including early stages of metastasis seeding in the brain." (PMID 26706037, 2016). "Furthermore, stimulation of CD137 on tumor endothelial cells via an agonistic antibody upregulates ICAM1, VCAM1, and E-selectin and thereby enhances T-cell recruitment into tumor tissue." (PMID 26500646, 2015). "After this initial interaction, firm adhesion takes place, mediated by several cell adhesion molecules belonging to the integrin family as well as the Intercellular Adhesion Molecule-1 (ICAM-1) and Vascular Cell Adhesion Molecule-1 (VCAM-1) from the immunoglobulin family, leading to tumor invasion." (PMID 24857933, 2014). "Furthermore, we demonstrated that knockdown of endogenous VCAM-1 expression in MDAMB231 cells reduced tumor formation in a SCID xenograft mouse model." (PMID 24583847, 2014). "In another work a VCAM-1-mediated tumor immune evasion has been described." (PMID 25030093, 2014). "Reduced VCAM-1 expression in tumors, along with reduced recruitment of macrophages to the tumor site, may therefore be responsible for decrease in tumor cell metastasis to the lungs of mice bearing CXCR7-downregulated tumors." (PMID 24886617, 2014). "In HCC, serum VCAM-1 level appears to reflect the severity of the underlying chronic liver disease rather than the tumor status, and low preoperative serum VCAM-1 levels are predictive of better disease-free survival after surgery." (PMID 24829073, 2014). "In vivo studies reveal that immunoliposomes conjugated with different ligands to target specific tumor antigens, for example, VCAM-1, interleukin-13, and EGFR, may be of important clinical significance as a novel treatment for cancer." (PMID 24175095, 2013). "Similarly, radiation-induced damage can upregulate expression of vascular cell adhesion molecule 1 (VCAM-1) on tumor vessels, thus facilitating T cell migration." (PMID 22973551, 2012). "Furthermore, in each tumor dataset tested, we found a significant positive correlation between VCAM1 gene expression and IREG score." (PMID 23056240, 2012). "Furthermore, RT modifies the tumor microenvironment by enhancing the release of CXCL16 from tumor cells and upregulating VCAM-1 on the tumor vasculature to favor the recruitment and trafficking of tumor specific cytotoxic T cells to tumor tissue." (PMID 22666458, 2012). "While both regimens induced the activation and expansion of anti-tumor T cells, and increased VCAM-1 expression on tumor endothelium and T cell infiltration in the tumor, the regimen of 3 Gy × 5 failed to cause a significant inhibition of tumor growth." (PMID 23112958, 2012). "For example, the vascular cell adhesion molecule-1 (VCAM-1) up-regulated in cancer cells grown as a co-culture with CAFs may be involved in tumor progression and metastasis particularly via lymphangiogenesis promotion." (PMID 22453032, 2012). "Not only does VEGF increase vascularity at sites of inflammation but its production by tumour cells results in the expression of inter-cellular adhesion molecule-1 and vascular cell adhesion molecule-1, thereby facilitating the adhesion of leukocytes to endothelial cells." (PMID 20222950, 2010). "Our current working hypothesis is that the tumor cells can use adhesion molecules, such as VCAM-1, to interact with and adhere to the endothelial monolayers, essentially emulating leukocytes during the inflammatory reaction." (PMID 19930605, 2009).
tumor (continued). "Furthermore, endothelial cells, such as pulmonary endothelial cells have been shown to coexpress CXCL12 and vascular cellular adhesion molecule (VCAM)-1, thus mediating tumour-cell/endothelial-cell attachment." (PMID 16819541, 2006). "In addition to their anti-inflammatory activity against IBD, anti-VCAM-1 antibodies may also pose a therapeutic benefit in preventing tumour proliferation and metastasis in CRC." (PMID 40095109, 2025). "However, it is possible that reduction in VCAM1 could also impede T cells from infiltrating into the tumor." (PMID 40953263, 2025). "Based on this review, a specific focus on expression of L-Selectin and VCAM-1 could have a promising anti-tumoral effect through their capacity to enhance anti-tumor immunity alone or in combination with immunotherapy while not being so involved in cancer cell dissemination." (PMID 40071851, 2025). "Furthermore, the VCAM1 protein, classified within the immunoglobulin superfamily, is stimulated by inflammatory mediators, and its overexpression can facilitate the evasion of tumor cells from the immune system response and inhibit the activity of ROS." (PMID 39997745, 2025). "One such adhesion molecule is vascular cell adhesion molecule 1 (VCAM-1), which is upregulated very early in brain metastasis formation and has also been shown to enhance endothelial cell recruitment for new blood vessel formation, thus supporting tumour growth and spread." (PMID 39000268, 2024). "Next, we tested whether VCAM1 in human tumor cells inhibited human iNKT cell activation." (PMID 38332012, 2024). "VCAM-1 has previously been implicated in the adhesion of monocytes to conventional vascular endothelial cells, such as human umbilical vein endothelial cells (HUVEC) and human aortic endothelial cells (HAEC), and is highly present on the vasculature and sinusoids of HCC tumours." (PMID 39684877, 2024). "Additionally, higher VCAM1 but lower ICAM1 was detected in tumor tissues than in normal tissues." (PMID 38332012, 2024). "Notably, knockdown of Vcam1 increased apoptosis of MC38 tumor cells." (PMID 38332012, 2024). "VCAM1 may be related to poor prognosis and tumor metastasis." (PMID 38516703, 2024). "Accordingly, tumor cells were extracted for subpopulation analysis, and the identified malignant cells clustered into eleven subclones: BRCA_SRGN, BRCA_SLC39A6, BRCA_ITGB3, BRCA_PECAM1, BRCA_PPP1R1B, BRCA_VCAM1, BRCA_ICAM1, BRCA_S100A9, BRCA_GLUL, BRCA_TASTD2 and BRCA_AGR3." (PMID 37626402, 2023). "Thus, reducing VCAM-1 expression offers hope for inhibiting the metastasis of tumor cells." (PMID 36839671, 2023). "Therefore, by combining the vascular cell adhesion molecule VCAM-1 on tumour cells with the integrin protein, the tumour-targeting recognition effect of the macrophage membrane could be achieved." (PMID 35931744, 2022). "First, scanning the available oncomine database reveals that a majority (41 out of 49) of human OS tissues over-expressed VCAM-1, suggesting the possibility that VCAM-1/VLA-4 signaling may similarly promote tumor survival, metastatic progression and immune evasion in metastatic OS." (PMID 36497180, 2022). "Moreover, it interferes with the infiltration and delivery of functional T cells towards the tumor, downregulates the expression of intercellular adhesion molecule-1 (ICAM-1) and vascular cell adhesion molecule-1 (VCAM-1), and develops the loss of antitumor immunity and immunotherapeutic resistance." (PMID 36686754, 2022). "In addition, oncogenic Kras driven metabolic reprogramming in pancreas cancer cells utilizes cytokines from tumour microenvironment, and tumour‐associated macrophages in tumour microenvironment promote progression and the Warburg effect via the CCL18/NF‐kB/VCAM‐1 pathway in PDAC." (PMID 33942483, 2021).
tumor (continued). "Although the clinical activity as single agent is modest, it has been shown that anti-angiogenic drugs could normalize the tumor vasculature and increase T cell infiltration by inducing the upregulation of the leukocyte adhesion molecules such as ICAM-1 and VCAM-1 on tumor endothelial cells." (PMID 34956912, 2021). "We hypothesized that ADAM12 affects some cytokines required for angiogenesis in the tumor microenvironment via specific signaling pathways, such as vascular cell adhesion molecule 1 and vascular endothelial cadherin, and mediates tumor angiogenesis to subsequently promote tumor progression." (PMID 34604068, 2021). "Moreover, monocytes closely adhere to GBM via VCAM-1 and promotes tumor invasion activity." (PMID 33959130, 2021). "Integrin αvβ3, stemness marker CD44 expressed by bone matrix and vascular cell adhesion molecule 1 (VCAM-1) which is constitutively expressed on bone marrow endothelial and stromal cells, lead to bone specific homing when respective molecules are expressed on tumor cells." (PMID 34063821, 2021). "Similarly, when we calculated tumor growth rate over day 11 to day 15 and compared the reduction of tumor growth rate, we observed less reduction of tumor growth rate in VCAM-1-overexpressing tumors compared to control tumors (38.4% vs 71.3% reduction, respectively)." (PMID 33273652, 2020). "Indeed, sunitinib treatment resulted in upregulated expression of ICAM-1 and VCAM-1 adhesion molecules on endothelial cells of tumor bearing mice, with several studies reporting that infiltration of TILs is markedly increased in animal tumor models and in humans after VEGF inhibition." (PMID 33121034, 2020). "Furthermore, researchers discovered that tumor cells' overexpression of VCAM1 accomplished lung or bone metastasis by recruiting monocytes or macrophages and forming a complex that facilitates circulating tumor cell evasion from immune system attack and trans-endothelial migration." (PMID 32793471, 2020). "Anti-VCAM-1 Nbs have been used to tag microbubbles and applied for the visualization of tumor vasculature by ultrasound imaging: contrast-enhanced ultrasound imaging showed an increased echo signal intensity in cancer tissue already 10 min after VCAM-1 Nb-coated microbubbles compared to control." (PMID 33353213, 2020). "Thus, we investigated whether FUS-induced inflammation led to differences in expression of cell adhesion molecules E-selectin, P-Selectin, ICAM-1, and VCAM-1 on intracranial B16F1cOVA tumor CD31+ endothelial cells 6 hours post FUS+MBs BTB/BBB opening." (PMID 32754281, 2020). "Indeed, VCAM-1 expression on endothelial cells plays a key role in angiogenesis, in tumor cell transmigration, and therefore promotes tumor development and dissemination of tumor cells." (PMID 31340603, 2019). "Moreover, an aberrant expression of VCAM-1 has been observed in tumor cells." (PMID 31338363, 2019). "Indeed, treatment with angiogenesis inhibitor anginex significantly up-regulated the expression of VCAM-1 and E-selectin on tumor blood vessel endothelial cells resulting in increase in tumor-infiltrating leukocytes and suppression of tumor growth in mouse models of cancer." (PMID 31231358, 2019). "Therefore, it is probable that decreased expression of IL-18 in the current study may have abrogated the expression of VCAM-1, which possibly contributed to the reduction of tumor incidence." (PMID 30401976, 2018). "Thus, it can be suggested that the higher VCAM-1 expression in the primary tumours may be helpful in predicting DFS in female PTC patients and also the extent of treatment that might be required in the PTC patients with VCAM-1 overexpression." (PMID 26881177, 2016). "Thus, CXCR7 may regulate endothelial adhesion, at least in part, through modulation of downstream VCAM-1 levels and targeting CXCR7/VCAM-1 may provide a novel opportunity to prevent tumor invasion and metastasis." (PMID 25084358, 2014).